DHRSX (dehydrogenase/reductase X-linked)
Description:
Oxidoreductase that plays a key role in early steps of protein N-linked glycosylation by mediating two non-consecutive steps in dolichol biosynthesis. Acts both as a NAD(+)- dependent dehydrogenase and as a NADPH-dependent reductase during the conversion of polyprenol into dolichol. First catalyzes the NAD(+)-dependent dehydrogenation of polyprenol into polyprenal; polyprenal is then reduced into dolichal by SRD5A3. It then catalyzes the NADPH-dependent reduction of dolichal into dolichol. May also acts as a positive regulator of starvation-induced autophagy.
Synonyms: CXorf11; DHRS5X; SDR46C1; SDR7C6; DHRSXY; DHRSY; DHRS5Y; CDG1DD
Tractability: Antibody: UniProt places it where antibodies can reach, with high confidence; its Gene Ontology location is reachable by antibodies, with high confidence. PROTAC: ubiquitination databases record sites on it; its protein half-life has been measured.
Gene: Protein-coding gene on chromosome X (2,219,506 to 2,502,805, reverse strand). Ensembl gene ENSG00000169084.
Subcellular location: Lipid droplet; Secreted
Subcellular location (Human Protein Atlas): Cytosol; Mitotic spindle; Predicted to be secreted
Pathways (Reactome):
Metabolism of proteins: Synthesis of dolichyl-phosphate
Gene Ontology:
Molecular function: alcohol dehydrogenase (NADP+) activity; dolichal reductase (NADPH) activity; polyprenol dehydrogenase (NAD+) activity; protein binding; alcohol dehydrogenase (NAD+) activity
Biological process: dolichyl monophosphate biosynthetic process; positive regulation of autophagy
Cellular component: extracellular region; lipid droplet; endoplasmic reticulum membrane
Homologues: Orthologues: dog DHRSX (66% identical), tropical clawed frog dhrsx (64% identical), zebrafish si:dkey-23o4.6 (36% identical), Drosophila melanogaster CG2065 (35% identical), zebrafish zgc:153441 (34% identical), Caenorhabditis elegans dhs-22 (29% identical). Paralogues in human: RDH13 (38% identical), RDH14 (36% identical), DHRS13 (29% identical), KDSR (20% identical).
Diseases named in the same sentence as DHRSX in open-access papers:
DHRSX is named in the same sentence as 4 diseases in open-access papers, as found by Europe PMC text mining. Sharing a sentence is not in itself a finding about the gene and the disease. The quoted sentences say what the papers report.
Autoimmunity (1 paper, 2025). The occurrence of an immune reaction against the organism's own cells or tissues. "DHRSX can cause redox imbalances in thyroid cells, exacerbating antigen presentation and autoimmunity." (PMID 39891056, 2025).
leukemia (1 paper, 2024). A malignant (clonal) hematologic disorder, involving hematopoietic stem cells and characterized by the presence of primitive or atypical myeloid or lymphoid cells in the bone marrow and the blood. "The promotion of autophagy by DHRSX involves the downregulation of AKT/mTOR phosphorylation and the upregulation of beclin-1, which are highly related to the antiapoptotic function and chemotherapy resistance of leukemia cells." (PMID 38811988, 2024).
tumor (2 papers, 2016 to 2021). "Being that several PAR genes are implicated to function as tumor suppressors, such as PPP2R3B, SHOX, SLC25A6, ASMT, and DHRSX, they serve as prime candidates for further investigation and may hold the greatest therapeutic promise." (PMID 27655702, 2016). "The genes that appeared most frequently among the top projected targets for the 15 patient tumor samples were SLC24A1, ARTN, DHRSX, TEX261, and FRMD8." (PMID 34662337, 2021).
DHRSX also shares sentences with these, for which no sentence is quoted: Infertility (1 paper).